EGFR (epidermal growth factor receptor)
Diseases named in the same sentence as EGFR in open-access papers (continued):
Sharing a sentence is not in itself a finding about the gene and the disease.
emphysema (28 papers, 2011 to 2025). "The wild type status for EGFR was predicted by the appearance of emphysema and airway abnormality while the presence of any ground glass component indicates EGFR mutations." (PMID 35330479, 2022). "Past studies found that the radiological characteristics of maximum diameter, location, density, lymphadenopathy, spiculation, vacuole sign, air bronchograms, pleura retraction, emphysema, and fibrosis were associated with EGFR mutation status." (PMID 34807270, 2022). "A plausible reason for this is that EGFR mutation status have a stronger association with non‐emphysema status." (PMID 35081265, 2022). "Their results suggest that wild-type EGFR is associated with conditions such as emphysema and airway malformation, while EGFR mutations are associated with ground-glass opacity changes." (PMID 32185138, 2020). "As well as gender, smoking history and GGO, adenocarcinomas with EGFR mutations were significantly associated with emphysema, TDR, and the diameter in mediastinal window." (PMID 28988295, 2018). "As well as gender, smoking history and GGO, adenocarcinomas with EGFR mutation were significantly associated with emphysema, TDR, and the diameter in the mediastinal window." (PMID 28988295, 2018). "Although the frequency of EGFR mutation was low in patients with emphysema and fibrosis, the frequency in those with normal lungs was not different between smokers and never-smokers." (PMID 22191026, 2011). "This indicates that CT findings of emphysema or fibrosis may be possible to predict the presence of EGFR mutations." (PMID 34807270, 2022). "In terms of radiographic features, 9 features, including size, margin, shape, pleural retraction, bronchiole change, lobulation, speculation, peripheral emphysema, peripheral fibrosis were significantly associated with EGFR mutation status." (PMID 31993370, 2019). "The presence of emphysema is strongly negatively correlated with the presence of EGFR (Q-value 1.02E-05), whereas the larger the ground glass component of a lesion, the more likely the lesion tested positive for an EGFR mutation (Q-value 6.99E-06)." (PMID 28139704, 2017). "The results showed an advantage in the Cryo-Radial diagnostic rate and EGFR detection capacity compared to CT-TTB, and a lower risk of emphysema." (PMID 40661124, 2025). "We therefore assessed the effect of EGFR inhibition in a mouse model of elastase-induced emphysema combined with RV infection, in which many features of human COPD exacerbation, including mucus hypersecretion, are recapitulated." (PMID 35239513, 2022). "In this study, compared with non‐ALK&ROS1/EGFR mutations in NSCLC patients, patients with EGFR mutation had a lower incidence of pulmonary emphysema." (PMID 35081265, 2022). "The expression correlation between AHR, LRIG1, and EGFR was examined in normal, emphysema, and chronically inflamed lung tissues (emphysema and chronic bronchitis are typical symptoms of COPD)." (PMID 34576152, 2021). "Contrarily, the AHR and EGFR were poorly expressed in emphysema and chronic bronchitis lung tissues but were dominantly found in epithelial cells of normal lung tissue." (PMID 34576152, 2021). "In our study, we quantitatively measured some of the CT parameters, such as diameter, TDR, Erel, emphysema, and found that gender, smoking history, emphysema, diameter and TDR had some predictive value in wild-type and different EGFR mutation subtypes." (PMID 28988295, 2018). "The top predictive features for EGFR are related to the presence of emphysema and the amount of ground glass in the lesion." (PMID 28139704, 2017). "The presence of emphysema is at the root of the tree, determining EGFR wild type tumors, followed by tumors with airway abnormalities also determining EGFR wild type tumors." (PMID 28139704, 2017).
emphysema (continued). "Using small molecule inhibitors to block the EGFR pathway could potentially inhibit BC cell growth while simultaneously reducing emphysema-related lung lesion progression, providing patients with more precise and effective treatment options." (PMID 41036447, 2025). "Moreover, gender, smoking history, emphysema, diameter in the mediastinal, TDR, and GGO showed statistical differences between the wild type group and mutated group of EGFR." (PMID 35330479, 2022). "EGFR mutation was more likely to be found in groups with smaller size, adenocarcinoma and without emphysema, COPD, and ILD." (PMID 34807270, 2022). "The connection between EGFR mutation and internal air bronchogram, pleural retraction, emphysema, and lack of smoking was found." (PMID 35330479, 2022). "We also found that the frequency of EGFR mutations was higher in patients without emphysema or fibrosis than patients with emphysema or fibrosis, which is consistent with results of a prior study." (PMID 34807270, 2022). "The results showed that exon 19 deletion EGFR mutation was associated with gender, smoking history, the MaxDmediastinal, TDR, GGO and emphysema grade, and the exon 21 missense mutation was associated with gender, smoking history, and the MaxDmediastinal and MinDmediastinal." (PMID 28988295, 2018). "EGFR mutation was seen more frequently in female patients (57/100, P < 0.001), non-smokers (78/100, P < 0.001), and normal and less severe emphysema patients (95/100, P = 0.016)." (PMID 28988295, 2018). "EGFR-TKI treatment should be considered in patients with an EGFR mutation, even if they have a history of smoking or emphysema without fibrosis." (PMID 22191026, 2011). "Although a history of smoking and the coexistence of emphysema were negatively associated with the frequency of EGFR mutations, these clinical factors did not affect the prognosis of the patients with EGFR mutations treated with gefitinib." (PMID 22191026, 2011). "Compared with EGFR wild type, EGFR exon 19 mutation has some distinct clinicoradiologic characteristics, including the female gender, pleural retraction, small lesion diameter, the absence of emphysema and fibrosis." (PMID 30235778, 2018). "A total of 132 adenocarcinoma patients underwent EGFR gene testing, including 49, 30, and 53 patients combined with IPF, emphysema, and normal lung in chest HRCT, respectively." (PMID 40507634, 2025).
clear cell renal cell carcinoma (27 papers, 2012 to 2026). "According to recent studies, there is a significant association between OPN and EGFR expression in clear cell renal cell carcinoma." (PMID 34257527, 2021). "Overexpression of EGFR is associated with tumor initiation and progression in several solid tumors, including clear-cell renal cell carcinoma (cRCC)." (PMID 29928482, 2018). "Although prognostic significance of EGFR was confirmed in numerous studies, the association between EGFR expression and prognosis in clear cell renal cell carcinoma (CCRCC) is still controversial." (PMID 22475688, 2012). "Notably, studies have shown that EGFR expression is closely associated with prognosis in patients with clear cell renal cell carcinoma." (PMID 41300698, 2025). "Overexpression of epidermal growth factor receptor (EGFR) is known to promote tumor initiation and progression in clear-cell renal cell carcinoma (cRCC)." (PMID 29928482, 2018). "Furthermore, it has demonstrated inhibitory effects on tumor growth and metastasis in clear cell renal cell cancer through suppression of the EGFR signaling pathway." (PMID 39430741, 2024). "EGFR is a valuable target for treating several cancers, notably renal clear cell carcinoma." (PMID 38008826, 2023). "Additionally, miR-514a-3p was identified as a novel tumor suppressor, with functional assays demonstrating its capacity to inhibit cell proliferation by targeting the epidermal growth factor receptor in clear cell renal cell carcinoma." (PMID 38274754, 2023). "Furthermore, “The Cancer Proteome Atlas” resource enabled us to investigate kidney cancer subtype specific expression of EGFR, indicating that this receptor is a specific biomarker for clear cell renal cell carcinoma." (PMID 36221114, 2022). "EGFR is overexpressed in the majority of clear cell renal cell carcinomas (CCRCCs)." (PMID 34445451, 2021). "The role of epidermal growth factor (EGF) and its receptor (EGFR) in the pathogenesis and progression of various malignant tumors has long been known, but there is still disagreement concerning prognostic significance of EGFR expression in clear cell renal cell carcinoma (CCRCC)." (PMID 22475688, 2012). "In contrast to normal tissues, STAT3-dependent EGFR and PAR-1 activation in endothelial cells OF clear cell renal cell carcinoma was significantly increased." (PMID 29291033, 2017). "In contrast to normal tissue, STAT3-dependent transactivation of EGFR and PAR-1 in endothelial cells of clear cell renal cell carcinoma was significantly increased." (PMID 29291033, 2017).
diffuse astrocytoma (27 papers, 1997 to 2025). A low-grade (WHO grade II) astrocytic neoplasm. "A group of 157 patients, classified as WHO grade 3 anaplastic astrocytoma (78.3%) and WHO grade 2 diffuse astrocytoma (21.7%), participated in a multicenter study to explore the impact of EGFR amplification and TERT-promotor mutation on overall survival (OS)." (PMID 38539537, 2024). "Hscore (median values and confidence interval) for p4E‐BP1, 4E‐BP1, peIF4E, eIF4E, EGFR, pS6, and pMAPK in gliosis cases, grade II diffuse astrocytomas, AA, and GBM." (PMID 27440383, 2016). "The other low-grade GLs, diffuse astrocytoma (cases 1, 3, 5 and 6) that showed histological progression to anaplastic GLs, 1 primary GB (case 16) and 2 giant cell GB (cases 17 and 18) the EGFR promoter region was sensitive to digestion by both HpaII and MspI." (PMID 22264301, 2012). "EGFR, c-erbB-2 and c-erbB-3 have been shown to be involved in the development and growth of diffuse astrocytomas." (PMID 22011735, 2011). "However, since 2022, the new WHO classification has added more genetic mutations that classify diffuse astrocytoma as grade IV gliomas (homozygous CDKN2A/B deletion, TERT promoter mutation, EGFR gene amplification, and chromosome 7 gain/chromosome 10 loss)." (PMID 37534252, 2023). "Therefore, it is not surprising that the study patient with a non-enhancing tumor (grade II diffuse astrocytoma) did not demonstrate an accumulation of cetuximab-IRDye800, suggesting that decreased permeability may prevent the agent from reaching the tumor regardless of EGFR expression." (PMID 29623552, 2018).
hepatitis B (27 papers, 2020 to 2026). "KEGG enrichment analysis showed that the top five KEGG pathways with high counts included pathways in cancer, prolactin signalling pathway, EGFR tyrosine kinase inhibitor resistance, hepatitis B pathway, PI3K–Akt signalling pathway." (PMID 35287559, 2022). "Our research proposed that MTOR, MAPK3, and EGFR are directly involved in hepatitis B pathways." (PMID 35745580, 2022). "In a study on both hepatitis B-induced HCC cell lines as well as on tumor bearing mice, Rh2 also showed anti-proliferative potential by up-regulation of miR-491, which was shown to target the epidermal growth factor receptor (EGFR) and by reducing its expression to act anti-proliferative." (PMID 34295245, 2021).
intrahepatic cholangiocarcinoma (27 papers, 2008 to 2026). A carcinoma that arises from the intrahepatic bile duct epithelium in any site of the intrahepatic biliary tree. "Nonsense mutation at glutamic acid 384, within the segment 2 of the EGFR and c-Abl binding motif of ERRFI1, exists in sporadic intrahepatic cholangiocarcinoma and is associated with enhanced cancer regression upon EGFR inhibition." (PMID 34206547, 2021). "Silencing of FX and SLC35C1 inhibits Notch and EGFR/nuclear factor kappa B (NF-κB) signaling, thereby suppressing the growth and migration of intrahepatic cholangiocarcinoma cells." (PMID 40821120, 2025). "For instance, it has been found that the m7G mutation significantly increases the expression of genes involved in the cell cycle and the epidermal growth factor receptor (EGFR) pathway in intrahepatic cholangiocarcinoma (ICC)." (PMID 38201505, 2023). "For instance, taurolithocholic acid (TLCA) induces the growth of intrahepatic cholangiocarcinoma (CHC) cells via activating the epidermal growth factor receptor (EGFR)/extracellular regulated protein kinases (ERK1/2) and muscarinic cholinergic receptors." (PMID 36826857, 2023). "For example, overexpression of EGFR has been reported to be observed in 10.7%, 5.1%, 12.4% and 0% of cases of intrahepatic cholangiocarcinoma, extrahepatic cholangiocarcinoma, gallbladder cancer and ampulla of Vater cancer, respectively." (PMID 24212807, 2011). "Additionally, 6-alkynyl-fucose inhibited fucosylation in intrahepatic cholangiocarcinoma cells and consequently suppressed their tumorous characteristics, and the Notch and EGFR activity." (PMID 40821120, 2025). "They reported the existence of a correlation between the prognosis and EGFR expression, and the survival duration of EGFR-positive patients was significantly longer than that of EGFR–negative patients, both among cases of intrahepatic cholangiocarcinoma and extrahepatic cholangiocarcinoma." (PMID 24212807, 2011). "MUC13 interacts with EGFR to induce PI3K/AKT signaling through EGFR and its internalization inhibition, thus promoting the metastasis of intrahepatic cholangiocarcinoma (ICCA)." (PMID 41513618, 2026). "In certain cancers, notably intrahepatic cholangiocarcinoma, LAMC2 facilitates tumor growth and metastasis through molecular pathways including epidermal growth factor receptor (EGFR) signaling." (PMID 40725121, 2025). "YTHDF1 was overexpressed in intrahepatic cholangiocarcinoma (ICC) and closely correlated to short survival of ICC patients, which was by increasing the translation of EGFR in a m6A-dependent manner." (PMID 36707507, 2023). "In addition, YTHDF1 and YTHDF2 facilitate the advancement of intrahepatic cholangiocarcinoma (ICC) through increasing EGFR mRNA translation and IFIT2 mRNA decay, respectively." (PMID 36999016, 2023). "Nevertheless, a tumor suppressor role of FTO has been described in intrahepatic cholangiocarcinoma (ICC) by controlling different pathways, including EGFR, and by decreasing the stability of the oncogene TEAD2." (PMID 37369946, 2023). "In vitro and in vivo, the EGFR pathway genes and the genes involved in cell-cycle were scrupulously regulated by METTL1-mediated m7G tRNA modification and thus promoted intrahepatic cholangiocarcinoma (ICC) progression." (PMID 36118897, 2022). "The expression of EGFR is common in BTC, but an overexpression was described in a wide range (5–32%) of cases and is more frequently in intrahepatic cholangiocarcinoma (ICC)." (PMID 27429047, 2016). "The proportions of positive cases for EGFR, VEGF, and HER2 overexpression were 27.4, 53.8, and 0.9% in intrahepatic cholangiocarcinoma (IHCC), and 19.2, 59.2, and 8.5% in extrahepatic cholangiocarcinoma (EHCC), respectively." (PMID 18087285, 2008).
intrahepatic cholangiocarcinoma (continued). "Similarly, in intrahepatic cholangiocarcinoma (ICC), METTL1‐ driven m7G tRNA modification drives the translational efficiency of oncogenic transcripts, including EGFR signalling pathways and cell cycle genes, thereby contributing to cancer progression." (PMID 41208200, 2025). "Furthermore, it has recently been demonstrated that YTHDF1 enhances the translation efficiency of epidermal growth factor receptor (EGFR) mRNA through its m6A reader function, thereby promoting the progression of intrahepatic cholangiocarcinoma." (PMID 38202722, 2023). "In intrahepatic cholangiocarcinoma, the methylase METTL1 mediates m7G tRNA modification, selectively regulating the translation of oncogenic transcripts, including genes involved with the cell cycle and epidermal growth factor receptor (EGFR) pathways." (PMID 36313442, 2022).
acute kidney injury (26 papers, 2013 to 2025). Sudden and sustained deterioration of the kidney function characterized by decreased glomerular filtration rate, increased serum creatinine or oliguria. "EGFR, along with other ErbBs, is expressed in the kidney tubules and is physiologically involved in nephrogenesis and tissue repair, mainly following acute kidney injury." (PMID 39234105, 2024). "In another clinical trial with locally advanced or metastatic, MET-amplified, EGFR mutation-positive NSCLC, a case of acute renal failure was found in patients treated with osimertinib plus savolitinib." (PMID 39026680, 2024). "Experimental studies have shown that genetic or pharmacological EGFR inhibition ameliorates renal damage progression, whereas in acute kidney injury, EGFR activation can accelerate renal recovery." (PMID 35204752, 2022). "This study showed that the anti-EGFR drug renal toxicity is mainly related to renal failure in the context of digestive toxicity." (PMID 34885014, 2021). "With the exception of gefitinib and panitumumab, a significant disproportionality signal was found for all the studied drugs targeting EGFR, with at least one of the following: acute kidney injury, renal failure or renal impairment." (PMID 34885014, 2021). "Renal failure is inconstantly mentioned in the summary of product characteristics of anti-EGFR drugs." (PMID 34885014, 2021). "Renal failure is also uncommon as an adverse event of anti-epidermal growth factor receptor antibody." (PMID 30646927, 2019). "Previous reports suggest that EGFR-targeting medications can possibly trigger or exacerbate an IgA-mediated glomerular process leading to renal failure." (PMID 29348949, 2017). "EGFR was expressed in the kidney, so EGFR inhibitors may cause AKI, renal failure or renal impairment." (PMID 39026680, 2024). "Summary of selected studies highlighting the role of EGFR signalling in acute kidney injury (AKI)." (PMID 39234105, 2024). "Renal failure is also uncommon as an adverse event of anti-EGFR antibody." (PMID 30646927, 2019). "Acute kidney injury (AKI) has been shown by genetic knock out and pharmacological inhibition studies to be protected by early activation of the EGFR pathway, while sustained EGFR signaling leads to renal injury and fibrosis in experimental AKI." (PMID 40224489, 2025). "The effects of blocking the epidermal growth factor receptor (EGFR) in acute kidney injury (AKI) are controversial." (PMID 25390346, 2014). "Podocyte specific deletion of the epidermal growth factor receptor (EGFR) gene in mice prevents the development of crescentic glomerulonephritis and renal failure." (PMID 23349960, 2013). "The computational pathway analysis illustrated that JGF might inhibit renal failure through PI3K-Akt, MAPK signaling pathway, and EGFR tyrosine kinase inhibitor resistance." (PMID 36144196, 2022). "Up-regulation of EGFR has been described for CKD, but EGFR inhibition in models of acute kidney injury (AKI) may also have deleterious effects." (PMID 36675700, 2022).